IGF1 (insulin like growth factor 1)
Diseases named in the same sentence as IGF1 in open-access papers (continued):
Sharing a sentence is not in itself a finding about the gene and the disease.
cancer (continued). "The cohort of LS patients, treated or not treated by recombinant IGF-1, appears to be protected not only from cancer but also from diabetes, whereas taller stature is now regarded as a risk for several types of cancer." (PMID 25333772, 2014). "Beneficial effects of low IGF1 on human survival seem to be mostly observed in individuals susceptible to malignancy, and it is noteworthy that traditional mouse strains like C57BL/6 die primarily of cancer." (PMID 25486354, 2014). "IGF-1 may stimulate cancer angiogenesis in part by upregulating vascular endothelial growth factor (VEGF) expression, whereas IGFs (IGF-1 and IGF-2) promote vasculogenesis in embryonic stem cells through the upregulation of VEGF." (PMID 24765205, 2014). "Associations between IGF-1, IGFBP-3, and cancer risk vary by cancer site." (PMID 24829560, 2014). "IGF-1 level remained a significant predictor of survival duration in linear regression models after multivariable adjustment in females (P = 0.01) and individuals with a history of cancer (P < 0.01)." (PMID 24618355, 2014). "Both insulin and IGF-1 have been hypothesized to play a role on cancer promotion through the Akt/PI3K/mTOR cascade that promotes cell growth and proliferation." (PMID 24267900, 2013). "Conversely, the growth response of cancer cells to IGF-1 was 20-fold greater (P < 0.05)." (PMID 24103397, 2013). "The notion that metformin suppresses cancer growth through pathways other than insulin/IGF-1-dependent, indirect drug action has recently been supported by experiments in liver IGF-1-deficient (LID) mice, which had naturally decreased lung tumor multiplicity and burden compared with wild-type mice." (PMID 23986086, 2013). "The observations of Kalaany and Sabatini that cancer cells with constitutively activated PI3K mutations are proliferative in vitro in the absence of insulin or IGF-1 and form CR-resistant tumors in vivo illustrate this issue." (PMID 24280167, 2013). "IGF-1 overexpression leads to neoplastic transformation, cancer progression and metastasis." (PMID 24308813, 2013). "Despite this collective evidence, the auxiliary analysis above did not suggest that IGF-1 is an independent risk factor or an intervening factor for long-term cancer mortality." (PMID 23405181, 2013). "IGF-1 facilitates the establishment of both lung and colon cancer metastases in the liver." (PMID 23983688, 2013). "Serum IGF-1 and IGFBP-3 concentrations can be measured easily and could be of value as indicators of cancer risk." (PMID 24339922, 2013). "Neither IGF-1 nor IGFBP3 was associated with either all cancer death or lung death among men or women in the multivariate analysis." (PMID 23405181, 2013). "In multiple cell lines, IGF1-mediated MET activation suggests that this cross-talk may contribute to progression in several cancer types when both molecules are expressed." (PMID 24005867, 2013). "PI3K/Akt pathway is one of the important down-streams of IGF-1 pathway, and numerous studies have confirmed its role in the apoptosis of cancer cells, and could sensitisize these cancer cells to cisplatin." (PMID 23437382, 2013). "In vivo studies have expanded the understanding of the IGF-1 system and its therapeutic potential in cancer; however, in vitro results have been inconclusive and further study is needed to more precisely determine the therapeutic significance of these findings." (PMID 24103397, 2013). "One observational study showing a relationship between level of circulating insulin and cancer has suggested that cancer growth may be influenced by the insulin-IGF-1 signaling axis." (PMID 22719752, 2012). "IGF-1 also promotes angiogenesis and thus may be a key target in the prevention of cancer cell extravasation and metastasis." (PMID 22852056, 2012).
cancer (continued). "Elevated insulin and IGF-1 levels are related to various cancers, such as breast and colon cancers." (PMID 22778714, 2012). "Higher insulin levels may also increase the bioavailability of insulin-like growth factor-1 (IGF-1), a related mitogen that has been associated with increased risk of other cancers." (PMID 22127286, 2012). "Early life body size and circulating levels of IGF-1 and IGFBP-3 have been linked to increased risks of breast and other cancers, but it is unclear whether these exposures act through a common mechanism." (PMID 22894543, 2012). "Highl levels of IGF1 contribute to progression of malignant tumors." (PMID 22891085, 2012). "It is well known that serum levels of IGF-1 correlate with cancer incidence in humans." (PMID 23152806, 2012). "Furthermore, IGF-1 is a potent mitogen in cancer cells and plays an important role in tumorigenesis and tumor progression in a variety of cancers." (PMID 22485142, 2012). "Indeed, it has been reported that high IGF-1 and low IGFBP-3 levels in serum increase the risk of cancer." (PMID 22429812, 2012). "Given the known influence of zinc on modulation of IGF-1 concentrations, supplemental dietary intake of zinc may have the effect of stimulating cancer initiation and/or growth." (PMID 22852056, 2012). "Increasing evidence suggests that lycopene may modulate IGF-1 pathway, reducing IGF-1-stimulated cell growth in cancer cell lines decreasing IGF-1, IGF-1R, or increasing IGFBP-1 or IGFBP-3 in animal studies and in human subjects." (PMID 24212813, 2011). "Since incubation with low glucose medium reduced IGF1mRNA levels in adipocytes and since adipocyte conditioned media proliferative effect was reverted by inhibiting the IGF-1 pathway, the author suggests that adipocyte-produced IGF1 has a crucial role in promoting cancer cell growth." (PMID 21774820, 2011). "Several studies suggest that height and weight at birth are proportional to the level of IGF-1 in the umbilical cord, and that infants with higher percentile of height and weight at birth tend to develop more common cancers such as breast, prostate and colorectal later in life." (PMID 21729319, 2011). "Given IGFBP3's putative role as a negative regulator of IGF1 signalling, its anti-proliferative role and the negative correlation between serum IGFBP3 levels and cancer risk, we investigated a possible link between its expression and IGF1 signalling." (PMID 20840765, 2010). "Insulin-like growth factor-1 (IGF-I) signalling is important for cancer initiation and progression." (PMID 20051100, 2010). "Interestingly, not only is PI3K important for human cancer but is also part of the IGF-1 signaling pathway, which plays a well-established role in longevity." (PMID 20505758, 2010). "This dramatic reduction of DPP-IV in SCC suggests that an elevated level of intact IGF-1 may be present in the tumor niche of this cancer subtype." (PMID 23675206, 2010). "In addition it has recently been shown to be a critical regulator of embryonic growth regulating through IGF1, a growth factor frequently abnormally expressed in human cancer." (PMID 19221586, 2009). "Our results suggest that on the path of HPV16 induced transformation, cells acquire addiction to IGF1 but, when progressing to the fully malignant phenotype, they overcome this Achilles heel and re-establish robustness, characteristic of cancers refractory to therapy." (PMID 17622350, 2007). "Therefore, some cancers reported as occurring ‘before diagnosis’ may have actually developed during a long period of undetected GH and IGF-1 excess." (PMID 41293738, 2025). "This systemic insulin excess, along with the potential mitogenic effects of insulin and some insulin analogues, may promote tumour growth, possibly via stimulation of the insulin-like growth factor 1 (IGF-1) axis, a pathway implicated in the pathogenesis of several cancers." (PMID 41334715, 2025).
cancer (continued). "Moreover, MTF's ability to modulate insulin and IGF‐1 signaling contributes to its role in metabolic regulation and may have implications for cancer prevention and treatment." (PMID 39969135, 2025). "Thus, by modulating the IGF-1/IGFBP-3 axis, IF may lower cancer risk and enhance the effectiveness of anticancer therapies through inhibition of growth-promoting signals in tumor cells." (PMID 41008741, 2025). "The bioactive compounds in dairy could have both positive (linked to calcium, lactoferrin, and fermentation products) and negative (linked to insulin-like growth factor I (IGF-1)) effects on cancer development." (PMID 38397527, 2024). "Additionally, epidemiological studies in the general population have shown an association between increased circulating levels of GH’s central mediator, Insulin-like Growth Factor 1 (IGF-1), and certain types of cancer, underscoring the importance of remaining vigilant to this potential risk." (PMID 38505755, 2024). "However, it is questionable whether the impact of protein intake on IGF-1 concentrations is sufficient to observe altered cancer risks on a population level." (PMID 38643440, 2024). "Hence, the direct effect of DC on cancer cells may be influenced by the IGF1 axis activation status." (PMID 39450263, 2024). "Interestingly, laboratory-based mechanistic studies indicate that protein restriction may protect against cancer due to decreased systemic insulin-like growth factor 1 (IGF-1) signalling and a subsequent downregulation of intracellular mTor activation." (PMID 38643440, 2024). "In addition, insulin exhibits a mitogenic impact on the processes involved in carcinogenesis and may favor cancer development through IGF-1." (PMID 38785834, 2024). "Some of the work addressing the relation between IGF‐1 signaling and mitochondria was conducted on cancer cell lines due to previous reports suggesting that reductions of insulin and IGF‐1 pathway signaling might turn out to be beneficial in cancer prevention and therapy." (PMID 38924381, 2024). "The modulation of the gut microbiota may contribute to PCa development by influencing the insulin-like growth factor 1 (IGF1) signaling pathway through short-chain fatty acids, as well as by inducing autophagy in cancer cells and promoting the polarization of M2 cells." (PMID 39323879, 2024). "Therefore, medicinal plants and derived phytocompounds that can enhance the intracellular ROS and induce apoptotic cell death in cancer cells via modulating various molecular targets including IGF-1 could be potential therapeutic agents." (PMID 37560308, 2023). "Moreover, in the same mouse cancer model, resistance exercise resulted in the increased mRNA expression of insulin-like growth factor-1 (IGF-1) Ea isoform and myogenin in mouse muscles, which are both implicated in skeletal muscle regeneration and hypertrophy processes." (PMID 38136400, 2023). "In addition, PCa cells that had metastasized to bone showed an upregulated IGF-1 regulatory system, indicating that IGF-1 may promote cancer cell metastatic spread." (PMID 36831629, 2023). "Interestingly, metformin may also have a potential anticancer role, acting both directly on cancer cells and, indirectly, through the reduction of insulin and insulin-like growth factor 1 (IGF-1) levels." (PMID 36902406, 2023). "Neither rs35767 nor rs2614 were associated with cancer risk or IGF-1 levels in our study cohort." (PMID 38137390, 2023). "It was shown that IGF-1 secreted by irradiated CAFs’ binding to IGF-1R on CRC cells activated the AKT/mTOR pathway, causing glucose uptake and lactate release increasing solute carrier family 7 membrane 11 (SLC7A11) expression and promoting glutamine uptake by cancer cells." (PMID 36835075, 2023).
cancer (continued). "Thus, healthy cells could be selectively protected during chemotherapy and given the overall positive correlation between lower IGF-1 levels and decreased cell division activity the potential of IF for patients suffering from cancer seems enormous." (PMID 36235868, 2022). "Substantial efforts have been made to produce anti-cancer therapeutics that target components of IGF-1 signaling, which has resulted in the development of three major classes of inhibitors: anti-IGF-1R monoclonal antibodies, dual IR/IGF-1R tyrosine kinase inhibitors, and IGF neutralizing antibodies." (PMID 36556357, 2022). "Elucidation of the interplay between the IGF1 axis and additional pathways, including oncogenes and anti-oncogenes, will have a major impact on our understanding of basic molecular oncology processes as well as on our ability to design and optimize cancer therapies." (PMID 36479090, 2022). "Therefore, the cancer cell fate between dormancy and proliferation during tumor progression could be dictated by the interplay between IGF-1 and clusterin." (PMID 36430404, 2022). "CR and fasting may function by promoting a wide range of changes in metabolic pathways and cellular functions, including an increase in stress responses and a decrease in insulin-like growth factor-1 (IGF-1) and other growth factors that stimulate cancer cell growth and proliferation." (PMID 36432618, 2022). "Given the key role of IGF1 in the control of cancer cell metabolism, it is reasonable to assume that alterations in the expression and/or activity of IGF1-dependent metabolic genes may constitute an important mechanism in the establishment of a malignant phenotype." (PMID 36291127, 2022). "Given the fact that the IGF1 axis emerged in recent years as a promising therapeutic target, we believe that a careful exploration of this signaling system might be of critical importance on our ability to design and optimize cancer therapies." (PMID 36479090, 2022). "Grimberg indicated that circulating IGF-1 may be related to the risk of different types of cancer but does not have a causal role in cancer formation; local changes in mechanisms controlling cell growth are required." (PMID 35203722, 2022). "This may be due to the fact that IGF‐1 is directly involved in cancer pathogenesis." (PMID 34363732, 2021). "Accordingly, our results suggest that differences between plant vs. animal protein intake and cancer or cardiovascular risk do not arise from their effects on components of the IGF-1-system but protective properties of other components present in plant-based diets." (PMID 33686453, 2021). "The IGF-1/PI3K/AKT/mTOR signaling pathway may be one of the important mechanisms of cancer." (PMID 34696683, 2021). "This suggests that the effect of height on cancer risk operates via pathways independent of IGF-1." (PMID 34324486, 2021). "However, current experimental data supports the hypothesis that the GH/insulin-like growth factor-1 (IGF-1) status may facilitate carcinogenesis and influence cancer biology." (PMID 32349463, 2021). "Besides, promoter methylation of IGF-1R, IGF-1, IGF-II, and especially IGFBP-3 in various regions could be associated with cancer prognosis." (PMID 33768092, 2021). "Notably, cancer exhibited unique behavior compared to the other conditions; higher IGF‐1 was generally associated with increased hazard for incident cancer, with no significant trend across different ages (p=0.54)." (PMID 34363732, 2021). "Furthermore, considering the mitogenic nature of IGF-1, its interaction with receptors can be regulated by IGFBP-3, and upregulation of IGF-1/IGFBP-3 or a lower level of IGFBP-3 may increase the risk of cancer." (PMID 33815885, 2021). "Upregulated expression of growth factors such as IGF1, FGF7, proteases such as MMP2, ECM constituents such as SPP1 also known as osteopontin and chemokine such as CXCL12 may indicate the presence of cancer-associated fibroblasts (CAFs) within the tumor microenvironment." (PMID 34946170, 2021).
cancer (continued). "In addition, IGF1 was negatively correlated with miR-186-3p expression in cancer tissues." (PMID 34551673, 2021). "Therefore, in theory, giving GH or IGF1 antagonist treatment in cancer radiotherapy may increase the radiation sensitivity of cancer cells, and promote the effectiveness of radiotherapy." (PMID 34178997, 2021). "IGF-1 did not modify the association between height and cancer incidence." (PMID 32921791, 2020). "Thus, there is solid evidence that both GH and IGF-1 are important cancer drivers in humans." (PMID 33312162, 2020). "Furthermore, IGF-1 may stimulate cancer cell migration, acquisition of epithelial-mesenchymal transformation (EMT) and chemotherapy resistance." (PMID 33584548, 2020). "The receptor of IGF‐1 (IGF‐1R) with the combination of IGF‐1 could exert vital function in cancer such as regulating cancer stem cell, epithelial‐mesenchymal transition and tumour microenvironment, which further influence cancer progression, metastasis and angiogenesis." (PMID 32548873, 2020). "Besides, the serum concentrations of inflammatory cytokines, glucose, insulin and free IGF-1 are notably elevated in obese patients and provide a pro-tumorigenic environment that may explain the worse prognosis of obese patients with cancer." (PMID 33374289, 2020). "Recognition of this linkage prompted us to conduct a genomic profiling of LS patients aimed at identifying IGF1-dependent genes and signaling pathways that are differentially expressed in LS and that may shed information on the molecular foundation for cancer evasion in this condition." (PMID 33182502, 2020). "Indeed, metformin can interfere with cancer metabolism by interacting not only with the pathways of adenosine monophosphate kinase and the mammalian target of rapamycin, but also with insulin itself and IGF-1." (PMID 32708201, 2020). "Similarly, lowered IGF1 protein expression was noted in cancer tissue compared with normal mucosa." (PMID 32977489, 2020). "There was no strong evidence to support IGF-1 moderating the association between height and cancer." (PMID 32921791, 2020). "However, the shift in the balance between IGF1 isoforms towards IGF1Eb in CC might play a role in cancer development and progression." (PMID 32977489, 2020). "Additionally, Ingenuity Pathway Analysis (IPA) of siSNHG7-regulated genes showed that the top canonical pathways are Molecular Mechanisms of Cancer and IGF1 Signaling (p = 3.93E-09; 42/97 molecules altered) and the top molecular and cellular function is Cellular Growth and Proliferation." (PMID 32444795, 2020). "Thus, the evolutionary advantage of reduced peripheral IGF-1 and increased lifespan with respect to reduced cancer incidence and progression may be offset by a central deficit that serves minimal evolutionary impact." (PMID 31732912, 2020). "IGF-1 does not modify the associations between height and cancer risk." (PMID 32921791, 2020). "However, late life IGF-1 deficiency (relevant to humans) has only a modest effect on maximum lifespan in female but not in male mice, in part, by reducing cancer risk." (PMID 31732912, 2020). "Notably, insulin-like growth factor-1 (IGF-1) induced cancer cell growth in a 15-Lox-1-dependent manner since 13(S) HODE might regulate IGF-1 expression transcriptionally." (PMID 31288808, 2019). "Moreover, late-life IGF-1 deficiency (15 months) reduced cancer risk but had no beneficial effects on lifespan." (PMID 30774624, 2019). "Furthermore, previous studies have reported that insulin-like growth factor 1 (IGF1) signaling can regulate mitochondrial biogenesis markers in the steroidogenic cells of prepubertal testis, and is essential for mitochondrial biogenesis in cancer cells." (PMID 30935132, 2019). "Although IGF-1 expression is promoted by growth hormone, which plays an essential role in determining adult height with bone growth, a higher level of serum IGF-1 in taller adults than those of shorter adults may lead to an increased risk for cancer mortality." (PMID 29758048, 2018).